CPA3 (carboxypeptidase A3)
Synonyms: MC-CPA
Tractability: Small molecule: it belongs to a druggable protein family. Antibody: its Gene Ontology location is reachable by antibodies, with high confidence; UniProt predicts a signal peptide or a membrane-spanning region. PROTAC: its protein half-life has been measured; a small molecule that binds it is known.
Target class: Metallo protease; Metallo protease MC clan; Protease; Metallo protease M14A subfamily; Enzyme
Gene: Protein-coding gene on chromosome 3 (148,865,296 to 148,897,203, forward strand). Ensembl gene ENSG00000163751.
Subcellular location: Cytoplasmic vesicle, secretory vesicle
Subcellular location (Human Protein Atlas): Golgi apparatus; Nucleoplasm; Predicted to be secreted
Pathways (Reactome):
Metabolism of proteins: Metabolism of Angiotensinogen to Angiotensins
Gene Ontology:
Molecular function: metallocarboxypeptidase activity; carboxypeptidase activity; peptidase activity; zinc ion binding
Biological process: proteolysis; angiotensin maturation
Cellular component: extracellular matrix; extracellular region; secretory granule; transport vesicle
Genetic constraint (gnomAD): Loss-of-function variants: 25 observed, 29.53 expected, observed/expected ratio (o/e) 0.85, 90% interval 0.62 to 1.18. The upper end of that interval is the gene's LOEUF score, 1.18, which puts it in group 5 of 6, group 1 being the genes least tolerant of losing a copy. Missense variants: 400 observed, 363.54 expected, observed/expected ratio (o/e) 1.1, 90% interval 1.01 to 1.2. Synonymous variants: 132 observed, 129.23 expected, observed/expected ratio (o/e) 1.02, 90% interval 0.89 to 1.18.
Homologues: Orthologues: chimpanzee CPA3 (98% identical), macaque CPA3 (97% identical), dog CPA3 (84% identical), guinea pig CPA3 (83% identical), rat Cpa3 (82% identical), mouse Cpa3 (81% identical), rabbit CPA3 (68% identical), tropical clawed frog cpa3 (53% identical), Caenorhabditis elegans T06A4.1 (36% identical), Caenorhabditis elegans Y47G6A.19 (32% identical), Drosophila melanogaster CG3108 (32% identical), Drosophila melanogaster CG18585 (31% identical), and 17 more. Paralogues in human: CPB1 (49% identical), CPA6 (41% identical), CPB2 (40% identical), CPA1 (38% identical), CPA2 (37% identical), CPA4 (37% identical), CPA5 (36% identical), CPO (36% identical).
Diseases named in the same sentence as CPA3 in open-access papers:
CPA3 is named in the same sentence as 62 diseases in open-access papers, as found by Europe PMC text mining. Sharing a sentence is not in itself a finding about the gene and the disease. The quoted sentences say what the papers report.
asthma (35 papers, 2010 to 2025). "The gene CPA3, which overlapped with outliers in Arkansas, produces a protein that is released by mast cells and is associated with asthma and allergies." (PMID 41208600, 2025). "Altered expression levels of CPA3 have also been proposed as a diagnostic and prognostic marker in asthma and COPD." (PMID 35983043, 2022). "Notably though, a series of clinical investigations have suggested that there is an association between CPA3 expression and asthma and other chronic lung diseases." (PMID 40413367, 2025). "The association of the five genes CEACAM5, POSTN, TCN1, SCGB3A1, and CPA3 with asthma has been extensively identified and validated, and these are the most highly upregulated genes in patients with asthma, and CEACAM5 is associated with resting mast cells and eosinophils." (PMID 39963184, 2025). "A role in allergy extended beyond the TG-affected genes reported in the pathway databases, namely RP11-13A1.1 (a lncRNA implicated in fungal immune response) and CPA3 (a protease released by mast cells and basophils, whose expression is elevated in asthma patients)." (PMID 36725846, 2023). "Molecular analysis of human lung samples revealed that tryptase and carboxypeptidase A3 were among the most differentially expressed genes in asthmatics vs. control, with Type 2 high asthma associated with expression of tryptase and carboxypeptidase A3, but not chymase." (PMID 36713876, 2022). "Although mast cells from donors with asthma exhibited a similar frequency of cells expressing characteristic genes, the level of expression for some markers was lower in those with asthma, notably CPA3 expression decreased by ~55%." (PMID 40399607, 2025). "We identified 8 key genes (LOC100132287, CEACAM5, PRR4, CPA3, POSTN, LYPD2, TCN1, and SCGB3A1) associated with asthma by combining the LASSO regression model and the SVM-RFE method." (PMID 39963184, 2025). "The strongest evidence is seen in the two most differentially expressed modules M6 and M2, which have Th2-related hub genes (CEACAM5 and CPA3, respectively); both are upregulated in the asthma cases." (PMID 38806494, 2024). "In a mouse asthma model, a CPA3 inhibitor reduces lung CPA activity, protects against airway hyperactivity, and reduces goblet-cell hyperplasia." (PMID 37241840, 2023). "Using molecular phenotyping of human asthma samples, a third mast cell type (tryptase+/carboxypeptidase A3+/chymaselow) was identified that correlated with eosinophilic asthma and increased responsiveness to corticosteroids." (PMID 36713876, 2022). "Increased CPA3 expression in intraepithelial mast cells among Th2-high asthma patients was observed." (PMID 35550122, 2022). "For example, observations in patients with steroid-naïve asthma demonstrated elevated and robust levels of tryptase and CPA3 mRNA in airway epithelial brushings, whereas chymase transcripts were low." (PMID 33546258, 2021). "Direct comparison between the airways within severe asthma identified greater expression of mast cells proteases (CPA3, TPSB2, TPSAB1) in the peripheral airways." (PMID 28045928, 2017). "The asthma severity node was strongly connected with mast cell mediators, tryptase, chymase, and carboxypeptidase A3 and with IL-13– and IFN-γ–secreting CD8+ cytotoxic T cells (TC2 and TC1 cells, respectively)." (PMID 25746968, 2015). "Genes related to epithelial repair and mast cell infiltration including β-tryptase and carboxypeptidase A3 were upregulated by exercise challenge in the asthma group with EIB." (PMID 20052409, 2010). "Increased expression of both tryptase and CPA3 was also recently noted in the airway epithelium in asthma, suggesting that the expression of these proteases are increased in asthma, and further increased in patients with EIB." (PMID 20052409, 2010).
asthma (continued). "Mast cell proteases have been shown to impact lung bronchial epithelium by disrupting their morphology, and here, the strong inhibition of CPA3 expression by imatinib may help restore barrier integrity during asthma." (PMID 40399607, 2025). "In children with asthma, we found an FGL2-driven subnetwork for B cell proliferation and T cell activation associated with both PM2.5 and ozone exposure; a CLC- and CPA3-driven subnetwork for leukocyte differentiation associated with ozone; and a TNFRSF10C-driven subnetwork associated with PM2.5." (PMID 41430723, 2025). "In addition to many important asthma-related genes identified in the current study, basophil-specific gene signatures, such as Mcpt8, Ms4a2, Cpa3, Fcer1a, and Cd200r3 were highly expressed in the AM group." (PMID 40443683, 2025). "On the other hand, we cannot exclude that CPA3, despite its redundancy in the mouse asthma model, might have an impact on asthmatic settings in humans." (PMID 40413367, 2025). "Our initial hypothesis was that mast cell CPA3 might represent a target, based on the implication of CPA3 in human asthma." (PMID 40413367, 2025). "However, the utilization of transcriptomics has allowed for the identification of mast cell genes such as tryptase β2 (PSB2) and carboxypeptidase A3 (CPA3), both of which are highly expressed in the sputum of patients with severe asthma." (PMID 39194521, 2024). "Also strongly upregulated in asthma cases, was the network (M2) with hub gene CPA3 (log2FC = 0.54, q = 2.39 × 10−14)." (PMID 38806494, 2024). "CST1, POSTN, CPA3, and SERPINB2 were key genes that potentially linked AR and asthma." (PMID 36733482, 2023). "A possible role for CPA3 in regulating TH2 immunity has not been demonstrated although CPA3 expression has been linked to TH2 type of asthma in humans." (PMID 35865537, 2022). "It is, however, noteworthy that, as for asthma, CPA3 levels in COPD and IPF may be particularly elevated in the subcategory of patients that have a type 2 immunity and eosinophil signature." (PMID 35983043, 2022). "Previous studies have shown the elevated expression of CPA3 in asthma and anaphylactic shock." (PMID 33441161, 2021). "Therefore, the gene expression of CPA3 and IL-8 were found to be important when differentiating between the two asthma phenotypes as well as the severity of moderate-mild asthma." (PMID 31143187, 2019). "The present study adds to an accumulating body of evidence from gene-array studies that genes such as CLCA1, SerpineB2, MUC5AC, AGR2, CPA3, and tryptase are overexpressed in asthma, and suggests that these genes are more transcriptionally active in the EIB phenotype." (PMID 20052409, 2010). "Although larger follow-up studies are needed, from other studied linking luminal CPA3 to steroid sensitivity in asthma, it is tempting to speculate that local tissue content of elevated mast cell CPA3 mRNA may be a general marker of both type 2 immunity and steroid responsiveness." (PMID 35983043, 2022). "Carboxypeptidase A3 is an asthma associated protease identified in lung epithelium and is a significant mast cell marker and was found to be upregulated in 42 non-smoking asthma patients." (PMID 24409194, 2014). "We further used a one-to-one format for comparison and validated with the GSE63142 dataset The genes CEACAM5, PRR4, CPA3, POSTN, TCN1, CST1 (Cystatin-SN), CLCA1, TPSAB1 and NOS2 (Nitric oxide synthase 2) were highly expressed in patients with asthma." (PMID 39963184, 2025). "Venn diagram analysis results demonstrated that CST1, POSTN, CPA3, and SERPINB2 were not only candidate genes in key modules but also DEGs in AR and asthma." (PMID 36733482, 2023). "Previously reported overexpressed (IL-10, MSR1, PHLDA1, SERPINB2, and CD86) and underexpressed genes (CHI3L1, CPA3, IL-8, and PI3) in severe asthma were analyzed by RT-qPCR in peripheral blood mononuclear cells (PBMCs)." (PMID 37445432, 2023).
asthma (continued). "Differential expression of CPA3 and TPSB2 between central and peripheral airways in severe asthma was confirmed by RT-qPCR." (PMID 28045928, 2017). "Module M31 included the IL-13 response gene, CLCA1 and the mast cell marker carboxypeptidase A3 (CPA3), suggesting a greater expression of mast cell secreted proteases in peripheral airways compared to central airways in severe asthma." (PMID 28045928, 2017). "Evidence of increased CPA3 and elevated urinary tetranor-PGD-M, the major urinary metabolite of mast cell prostaglandin D2 (PGD2), suggests that mast cell activation plays a pivotal role in T2-independent severe asthma." (PMID 39194521, 2024). "Moreover, the expression level of CST1 was significantly positively correlated with the expression levels of POSTN, CPA3, and SERPINB2 in the bronchial epithelium of AR patients and in the nasal epithelium of asthma patients." (PMID 36733482, 2023). "Even so, the role of CPA3 in asthma has not been conclusively elucidated and needs further research." (PMID 37241840, 2023). "In addition, the volcano plot showed that CST1, POSTN, CPA3, and SERPINB2 were significantly up-regulated in the bronchial epithelium of asthma and nasal epithelium of AR." (PMID 36733482, 2023). "For example, MCs with an unusual protease profile, expressing tryptase and CPA3, but not chymase, have been identified in the airway epithelium of patients with “Th2 high” asthma." (PMID 36430453, 2022). "However, we showed recently that the absence of CPA3 did not influence the outcome in a mouse model of asthma, arguing against a major role for CPA3 in regulating allergic asthma." (PMID 40413367, 2025). "Both the six gene signature (6GS: CPA3, DNASE1L3, CLC, IL1B, ALPL, and CXCR2) and T‐helper 2 signature (TH2S: CLCA1, SERPINB2, and POSTN) are proposed as biomarkers in the identification of inflammatory phenotypes of asthma in induced sputum and epithelial brushings, respectively." (PMID 31903716, 2020). "A six-gene signature (CLC, CPA3, DNASE1L3, IL1B, ALPL, and CXCR2) can differentiate asthma patients from controls, discriminate inflammatory phenotypes of asthma and predict the ICS response, but this method is not currently available." (PMID 30598830, 2018). "A role for CPA3 in asthma has, however, not been conclusively demonstrated, although our recent findings suggested that CPA activity originating from CPA3 or other related carboxypeptidases could contribute to the pathology in experimental asthma." (PMID 36430453, 2022).
COVID-19 (9 papers, 2021 to 2025). A disease caused by infection with severe acute respiratory syndrome coronavirus 2. "We previously reported increased serum CPA3 levels in severe COVID-19 patients and its association with markers of inflammation during SARS-CoV-2 infection." (PMID 39596322, 2024). "Serum levels of serotonin have also been implicated in MSCs function/senescence in COVID-19, and serum levels of serotonin and carboxypeptidase A3 (CPA3) have been implicated in COVID-19 severity." (PMID 35095855, 2021). "Therefore, this study aims to evaluate the unique CPA3+ mast cell phenotype in the lungs of fatal COVID-19 cases and to investigate its novel association with the development of pulmonary fibrosis (PF)." (PMID 39596322, 2024). "CPA3 has a role in the “biogenesis of the fibrous component of the extracellular matrix” and it has therefore been implicated in the remodeling of the extracellular matrix and fibrosis in COVID-19." (PMID 35736349, 2022). "Moreover, serum levels of serotonin and carboxypeptidase A3 (CPA3) have been implicated in COVID-19 severity." (PMID 35095855, 2021). "Based on the accumulated data, the heightened inflammatory response in COVID-19 patients leads to enhanced mast cell activity and increased CPA3 expression, resulting in tissue damage and compromised repair processes that progress to fibrosis." (PMID 40700078, 2025). "Negative correlations were found between the absolute content of single CPA3-positive MCs in the autopsy material of the lungs of patients with COVID-19 and the content of blood monocytes." (PMID 38667325, 2024). "The content of chymase-positive MCs was significantly reduced in patients with COVID-19 in comparison with the controls, while the content of CPA3-positive MCs and their degranulation activity were higher in patients with COVID-19." (PMID 38667325, 2024). "Indicators of chymase-positive MCs in the lungs of patients with COVID-19 are presented in statistically significantly lower numbers than in controls, while the content of CPA3-positive MCs and their degranulation activity are higher in patients with COVID-19." (PMID 38667325, 2024). "We observed CPA3− MCs (CD117+, tryptase+, and CPA3−) and CPA3+ MCs (CD117+, tryptase+, and CPA3+) in both controls and COVID-19 patients." (PMID 39596322, 2024). "The CPA3+ cell count showed a significant increase in the total number of MCs in COVID-19 patients compared with the control group in pneumonic, thrombotic, and fibrotic areas areas." (PMID 39596322, 2024). "The purpose of this study was to determine the significance of MCs and their proteases chymase, tryptase, and CPA3 in the pathogenesis of lung damage in patients with COVID-19." (PMID 38667325, 2024). "In summary, these results suggest an unexpected role for CPA3 in pathological hyper-inflammation, such as during severe COVID-19." (PMID 39596322, 2024). "In the control group, CPA3+ cells were found throughout the alveolar–capillary interstitial tissue, whereas in COVID-19 patients, these cells were in areas with abundant leukocyte infiltration, in the wall of thrombotic vessels, and in areas with fibrosis." (PMID 39596322, 2024). "The objective of this study was to further reveal the importance of MCs and their proteases (chymase, tryptase, and carboxypeptidase A3 (CPA3)) in the development of lung damage in patients with COVID-19." (PMID 38667325, 2024). "The indicators of chymase-positive MCs (Chy-MCs) were significantly lower than in the controls, while the content of CPA3-positive MCs (CPA3-MCs) and their degranulation activity were higher in patients with COVID-19." (PMID 38667325, 2024). "MCs and their mediators have been associated with COVID-19; we previously reported the role of carboxypeptidase A3 (CPA3) in severe COVID-19." (PMID 39596322, 2024). "In control group tissues, few CPA3+ MCs were found, whereas in COVID-19 patients, a higher number of CPA3+ MCs were observed." (PMID 39596322, 2024).
COVID-19 (continued). "Serum CPA3 levels are correlated with “circulating neutrophils and CPR, which are associated with an exacerbated inflammatory response during COVID-19”." (PMID 35736349, 2022). "One study verified that serum levels of carboxypeptidase A3 (CPA3) increased in patients with COVID-19, and interestingly, serotonin levels decreased in serum from SARS-CoV-19 infected patients." (PMID 36532776, 2022). "Therefore, we next quantified CPA3+ cells in post mortem samples from COVID-19 patients and controls." (PMID 39596322, 2024). "However, our findings demonstrate that there is an increase in CPA3+ MCs associated with the pathophysiology of SARS-CoV-2 infection and the development of fibrosis owing to COVID-19." (PMID 39596322, 2024). "Furthermore, in a previous report, we showed that patients with severe COVID-19 had increased serum CPA3." (PMID 39596322, 2024). "There is also growing evidence of CPA3 involvement in the pathogenesis of COVID-19." (PMID 38667325, 2024). "Altogether, these results show an increased number of CPA3+ mast cells in COVID-19 patients." (PMID 39596322, 2024). "CPA3+ MCs were particularly abundant in pulmonary fibrotic areas of COVID-19 patients." (PMID 39596322, 2024). "Interestingly, we found that the increase in CPA3+ MCs counts correlated positively with PF in COVID-19 patients." (PMID 39596322, 2024). "The levels of the proteases in four patients subsequently deceased from COVID-19 were comparable to the levels in the patients with severe COVID-19: CPA3 (21.54 ±6.6 vs. 22.25 ±5.7 ng/ml, p = 0.72); CMA1 (2426 ±1113 vs. 2387 ±720 ng/ml, p = 0.73) and for TPSB2 (27.5 ±17 vs. 30.04 ±17 ng/ml, p=0.95)." (PMID 36225927, 2022). "In this study, we evaluated the presence of MCs in the lungs of fatal COVID-19 cases, finding an increase in the number of CD117+ and CPA3+ cells in pneumonic, peri-thrombotic, and fibrotic areas." (PMID 39596322, 2024). "In addition, the MC-derived protease genes, CPA3 and CMA1 (chymase), were not increased in COVID-19 patient lung tissue, consistent with the tissue-specific protease expression profile found in lung MCs." (PMID 33777047, 2021).